NF1 (neurofibromin 1)
Diseases named in the same sentence as NF1 in open-access papers (continued):
Sharing a sentence is not in itself a finding about the gene and the disease.
cancer (continued). "Because of the lack of effective treatments for preventing and treating NF1-related malignant tumors, our study provides the novel knowledge for developing new therapeutic strategies that can specifically antagonize diseases caused by Nf1-deficiency." (PMID 27741517, 2016). "Four genes (AKAP9, ATM, CREBBP, and NF1) were mutated in only one subject but were reported on the Cancer Gene Census list, and the mutations were predicted to be detrimental by SIFT." (PMID 27689332, 2016). "(iv) One male patient, who carried a stop-gain mutation (rs866445127) in NF1, had multiple skin (both basal cell and squamous) cancers." (PMID 27930734, 2016). "Via governing multiple downstream effectors, oncogenic or aberrant Ras promotes tumorigenesis, which is also proven to be the cause of the cancer predisposition of NF1 patients." (PMID 27741517, 2016). "Mutations of the NF1 gene in other types of cancer are associated with a highly aggressive often fatal outcome." (PMID 26643872, 2015). "In the MPNST, aside from the NF1 mutation, other mutations in cancer‐associated genes such as EHBP1 and WNK3 were identified." (PMID 26432421, 2015). "Inactivation of NF1 by germline mutations are predisposed to the development of benign and malignant tumors of peripheral and central nervous system including GBMs." (PMID 26317392, 2015). "As an example, we detected differentially expressed transcript variants of the cancer genes NF1 and MDM4." (PMID 26109056, 2015). "We then analyzed a subset of ~1,000 genes representing a molecular signature associated with NF1-peripheral nerve sheath tumors, differentiating benign tumors from malignant tumors and derived cell lines." (PMID 25810463, 2015). "In earlier work we mutagenized mice heterozygous for the Neurofibromatosis I tumor suppressor gene (NF1) to model radiotherapy-associated second malignant neoplasms that arise in irradiated NF1 patients." (PMID 26000738, 2015). "As would be expected from a cancer predisposition syndrome, individuals with NF1 are prone to the development of benign and malignant tumors, in this case, affecting the peripheral nervous system (PNS) and central nervous system (CNS)." (PMID 25243094, 2014). "Mutations of NF1 in AC were discovered through sequencing of a larger number of “suspected” cancer-related genes in a large number of tumors." (PMID 24722523, 2014). "Signal transducer and activator of transcription-3 (STAT3) is a potential target for treating NF1-associated or NF1-deficient cancers, as STAT3 is activated downstream in the PI3K/mTOR pathway." (PMID 25026295, 2014). "Individuals with NF1 are predisposed to developing both benign and malignant tumours throughout life." (PMID 25026295, 2014). "Individuals with NF1 are predisposed to benign and malignant tumors, which typically arise in cells derived from the embryonic neural crest." (PMID 24386979, 2014). "As for the cancer-related genes, for example, PC-7 harbored a splice site mutation in the NF1 gene, which is located in the splice donor site of the 19th intron." (PMID 25378332, 2014). "The reduced life expectancy of patients with NF1 has been attributed to NF1-associated malignant neoplasms." (PMID 23497412, 2013). "Of interest, this selection contained genes present in 5 out of 10 regions of homozygous loss found in our study and several genes known to be implicated in cancer and neuronal differentiation (such as NF1 and GAP43)." (PMID 23308108, 2013). "NF1 has been shown to reduce life expectancy by approximately 15 years, a reduction attributed to NF1-associated malignant neoplasms." (PMID 23497412, 2013). "As a comparison, only five known cancer genes that are mutated in >10 cancer types (NF1, EP300, BRCA2, MLL, ARID1A) are longer than 4,450 bp." (PMID 23718799, 2013). "Studies have suggested that patients with NF1 also have a significantly higher risk of certain types of carcinomas." (PMID 24137429, 2013).
cancer (continued). "Mutations in the NF1 gene result in abnormal cell growth and in the formation of benign and malignant tumors." (PMID 22747746, 2012). "It is this cellular dysregulation that explains much of the NF1 clinical phenotype, especially the increased risk of benign and malignant neoplasms evident in NF1." (PMID 23244495, 2012). "NF-1 is also associated with various benign and malignant neoplasms, including tumors of the nervous system and gastrointestinal tract." (PMID 22824559, 2012). "Gene expression profiling in NF1-associated benign and malignant tumours identified relatively widespread deregulation of genes in developing schawnn cells and in particular, the SOX9 gene seems to be essential for MPNST cell survival." (PMID 20687928, 2010). "The other approach used to study the risk of cancer in NF1 is to ascertain the number of cases of NF1 in a population of cancer patients." (PMID 16786042, 2006). "The overall risk of cancer was 2.7 times higher in this cohort of NF1 patients than in the general population (95% confidence interval (CI) 1.9–3.7)." (PMID 16786042, 2006). "Although both these studies verified the increased risk of cancer in NF1, there are problems with this type of study in terms of ascertainment bias." (PMID 16786042, 2006). "Similarly, NF functions as an endogenous inhibitor of RAS/RAF/ERK pathway and NF1 mutations are known to have a higher risk of cancerous tumors." (PMID 41155378, 2025). "The combination of atypical BRAF and other atypical Ras mutations (in KRAS, NRAS, or NF1) is consistent with a “mini-driver” model in which some cancers acquire sufficient Ras activation through a two-step process rather than a single “hit” at BRAFV600E or one of the common KRAS hotspots." (PMID 39751654, 2025). "Our methodology, built upon this unique NF1 dataset, may also extend to other cancer predisposition syndromes where early cancer detection of malignant transformation is critical." (PMID 40585258, 2025). "In addition to BC, somatic NF1 mutations have been observed in other cancers, including colorectal, lung, ovarian, bladder, melanoma, glioblastoma, and leukemia." (PMID 41155378, 2025). "People with NF1 are predisposed to developing both benign and malignant tumors." (PMID 41440192, 2025). "Notably, carrying a germline NF1 mutation increases the risk of BC and cancer-related mortality, particularly among women under 50 years of age." (PMID 41155378, 2025). "We asked whether compensatory RAS reactivation would be inhibited, and found that the addition of SHP2i to MEKi prevented RAS reactivation at 24 and 48 hours as measured by levels of GTP-bound RAS, comparable to the effect seen in NF1-deficient cancer models." (PMID 40900823, 2025). "Given that many of these miRNAs are already deregulated in other RAS-dependent cancers, their functional validation in NF1 could contribute to defining novel diagnostic or prognostic biomarkers and, potential new therapeutic targets." (PMID 41463204, 2025). "In this study, we applied a genome-first approach to interrogate the exome sequence of individuals in three large population and health system-based cohorts to quantify germline P/LP variant prevalence and examined cancer prevalence and survival of adults with non-NF1 RAS/MAPK P/LP variants." (PMID 39802765, 2024). "Furthermore, NF1 is associated with a genetic predisposition for the growth of both benign and malignant neoplasms." (PMID 38686623, 2024).
cancer (continued). "NF1 is a cancer predisposition syndrome associated with approximately 60% lifetime risk for cancer." (PMID 37460655, 2024). "The oncologic predisposition conferred by the NF1 mutation refers to the development of benign and malignant tumors; in particular, in childhood, the risk is increased for gliomas of the optic pathway, juvenile myelomonocytic leukemia, and embryonal rhabdomyosarcomas." (PMID 37627552, 2023). "In brief, a condition of oxidative stress could be indirectly related to the development of cancer in NF1-deficient cells by the increased activity of HSF1." (PMID 37627552, 2023). "Finally, those born with both NF1 and the perinatal factors of interest had indications of a higher risk of childhood cancer." (PMID 37490289, 2023). "NF1 is a rare genetic disease that can cause various benign or malignant tumors." (PMID 36629684, 2023). "Moreover, NF1 predisposes patients to both benign and malignant tumors, including nerve sheath tumors, gliomas, pheochromocytomas, and others." (PMID 37627552, 2023). "However, in cohorts of pediatric patients, rates of NF1-mutated cancers are significantly higher in females than in males." (PMID 36826025, 2023). "In addition, genetic testing revealed two unique germline mutations in the neurofibromin (NF1) gene, and their potential interaction in promoting cancer was further investigated." (PMID 37773168, 2023). "Thus, NF1 deficiency underlies the formation and/or progression of multiple cancer types beyond the neoplastic manifestations of neurofibromatosis." (PMID 37501682, 2023). "We hypothesize that NF1 mutation alone is not sufficient to induce the continuous activation of the RAS-ERK pathway and that the pathological activation of this pathway promotes the development of NF1-associated malignant tumors." (PMID 35625983, 2022). "NF1 mutations have been reported in 2.2% (7/313) of TNBC samples analyzed in the Catalogue of Somatic Mutations in Cancer (COSMIC, May 2020)." (PMID 36077638, 2022). "Focal adhesion, cAMP signaling pathways, and pathways in cancer were also under the most upregulated KEGG pathways in PPGLs with EPAS1 mutation compared with tumors bearing a mutation in one of the cluster 2 susceptibility genes (NF1, RET, MAX)." (PMID 35159368, 2022). "NF1 individuals have more than twice the risk of cancer of the general population." (PMID 35103797, 2022). "Moreover, the diagnosis of spinal tumors, especially in children, can be an indicator of a cancer predisposition syndrome such as NF1, NF2, and VHL syndrome." (PMID 34574050, 2021). "Interestingly, NF1-mutated cancers have a heavier mutational burden and thus exhibit a better response to immunotherapy than those with RAS or RAF mutations." (PMID 35582307, 2021). "A heterogeneous group of benign and malignant neoplasms are associated with NF-1." (PMID 34820071, 2021). "Patients with NF1 carry a higher overall lifetime risk for developing cancer." (PMID 34707296, 2021). "However, aside from cancer risk, distinctive clinical or neuroimaging features have been associated with specific NF1 variants." (PMID 33919865, 2021). "The presence of thyroid disease in NF1 may be linked to different mechanisms including autoimmune thyroiditis, metastasis of another cancer, thyroid neurofibromas, and thyroid cancer." (PMID 34025587, 2021). "Then, we further discuss advancements in targeted therapy for NF1-mutated malignant tumors." (PMID 33061844, 2020). "NF1 encodes a RasGTPase-activating protein (RasGAP) and its loss drives cancer by activating Ras." (PMID 33374737, 2020). "This might explain why, in contrast to nf1, single allele loss of suz12 in zebrafish is sufficient to promote the initiation of malignant tumors in a sensitized background." (PMID 32651197, 2020).
cancer (continued). "NF1-associated cancers appeared to be sensitive to bromodomain inhibition, indicating that PRC2 insufficiency might trigger an epigenetic switch that sensitizes these cancers to bromodomain inhibitors." (PMID 33374737, 2020). "In this case, we conclude the latest advancement in targeted therapy of malignant tumors with NF 1 mutations and further clarify the role of NF1 mutations in the treatment of malignancies to establish the viability of the treatment targeting NF1 mutations." (PMID 33061844, 2020). "NF1 is also mutated in various types of cancer, including melanoma, leukemia, and lung." (PMID 31836666, 2020). "In addition to germline variants, somatic NF1 alterations commonly occur in sporadic cancers and are associated with increased cancer risk and drug resistance." (PMID 32046255, 2020). "NF1 is a rare genetic disease which can cause various benign or malignant tumors." (PMID 31301733, 2019). "These tumors, characterised by high-grade cancer cells, bring out a critical diagnostic as well as therapeutic challenge for these patients, and about 50% of MPNSTs are diagnosed in association with NF1." (PMID 31694342, 2019). "NF1 is caused by a mutation in the tumor suppressor gene NF1 which leads to a decreased production of the protein neurofibromin and subsequently to the risk of developing benign or malignant tumors with a variety of clinical symptoms." (PMID 31301733, 2019). "Therefore, we extensively and systematically searched the literature for clinical data on NF1-associated benign and malignant tumors." (PMID 30479396, 2018). "In addition to germline mutations, NF1 mutations and deletions commonly occur in sporadic cancers and are associated with increased cancer risk and drug resistance." (PMID 30182054, 2018). "Neurofibromatosis 1 (NF1) is a dominantly inherited syndrome that predisposes to cancer." (PMID 29335026, 2018). "At first glance, this statement may seem paradoxical to the established cancer predisposition feature of the NF1 gene." (PMID 30479396, 2018). "Understanding the aetiology of cNF at the genomic level may assist in the development of new therapies for cNF, and may also contribute to a greater understanding of NF1/RAS signalling in cancers beyond those associated with NF1." (PMID 29695767, 2018). "Somatic NF1 mutations may be critical drivers in multiple cancers as well as contributing to resistance to therapy." (PMID 28637487, 2017). "Indeed, development of malignant tumors is regarded as the main cause for reduced life expectancy in patients with NF1." (PMID 29214122, 2017). "Indeed, most of the differentially mutated genes, cancer driver genes, and pathways identified in the present study had the highest mutation frequency in the NF1 subtype as compared to the other genomic subtypes." (PMID 28267273, 2017). "NF1 is associated with a wide variety of benign or malignant tumors." (PMID 28835241, 2017). "Presence of NF1 germline mutation suggests the patient may benefit from anti-MEK or anti-mTOR agents that are commercially available for other cancer indications." (PMID 27245685, 2016). "Interestingly, L1-NF1 expression in normal human tissues closely resembled the expression of cognate cancer-associated gene NF1." (PMID 27301971, 2016). "NF1 is a cancer predisposition disease with variable expressivity." (PMID 26161090, 2015).
cancer (continued). "Interestingly, next-generation sequencing of eight SDH-negative GIST cases using a targeted cancer-associated gene capture library identified a low-frequency (8 %) frameshift NF1 mutation in a GIST that also harbored an activating KRAS gene mutation (G12V)." (PMID 26555092, 2015). "Loss of NF1 also renders cancer cell resistant to apoptosis." (PMID 26317392, 2015). "Besides loss of NF1 function, additional aberrations in other important cancer‐related genes involving various pathways lead to the development of specific tumors." (PMID 26432421, 2015). "Individuals affected by NF-1 have an increased risk of developing both benign and malignant tumors." (PMID 25317349, 2014). "In addition to the prevalent cases of tumors and risk of cancers in NF1, there is an approximate 50% incidence of pediatric learning disorders." (PMID 24294527, 2013). "Individuals affected by NF1 harbor an increased risk for both benign and malignant tumors." (PMID 24167749, 2013). "Les cancers représentent la principale cause de décès prématuré des patients atteints de NF1." (PMID 24198875, 2013). "The molecular heterogeneity evident at a number of different gene loci indicates that there is an urgent need not only for the integration of molecular and morphological biomarkers in cancer diagnosis, but also for the development of specific treatments for NF1-associated MPNSTs." (PMID 23244685, 2012). "Pairwise comparison of targeted pharmacogenomic and comprehensive cancer panel sequencing-based mutation profiles between 5FU-resistant and matched parental cell lines identified a missense mutation in neurofibromatosis type 1 (NF1), c.5461G>T (V1821F) that is unique to the 45FU cell line." (PMID 39461475, 2024). "Individuals affected by NF1 have a high predisposition to develop varying numbers of neurofibromas, gliomas of the optic tract, other low-grade gliomas, and pheochromocytomas exhibit a benign course; however, they are at risk of developing malignancy or tend to develop into malignant tumors." (PMID 38893137, 2024). "Such modelling will allow us to define which patients are at high risk for malignant tumours and need specific screening; and may also help identify responses to new targeted therapies to improve survival in specific subgroups of individuals with NF1." (PMID 36684394, 2023). "Accordingly, NF1 may lead to malignancies, with a lifetime cancer risk of 60%." (PMID 36701730, 2023). "Accordingly, NF1 may lead to the development of malignancies, with a lifetime cancer risk of 60%." (PMID 36701730, 2023). "Similarly, targeting glutamine metabolism through GLS inhibition could provoke the lethality of ASS1-deficient cancers and is currently being evaluated in GIST and NF1-mutated cancers." (PMID 34294128, 2021). "Therefore, in cancer, NF1 mutations act not only as drivers but contribute to therapy resistance." (PMID 35008787, 2021). "Therefore, intraductal injection of a virus carrying gRNA could be used to mutate NF1 and other genes associated with human ER+ cancer to generate somatic models of ER+ cancer in rats." (PMID 33842308, 2021). "The protein encoded by the NF1 gene, neurofibromin, acts as an inhibitor of both classic Ras and R-Ras proteins; loss of neurofibromin could cause these Ras proteins to become persistently active, leading to the development of cancer." (PMID 34530870, 2021). "The same group estimated variants in one of 156 cancer predisposition genes among 2450 adult CCSs using whole-genome sequencing, with 11.8% of them carrying a pathogenic/likely pathogenic variant, and they frequently detected variants of Rb1, NF1, and BRCA2 genes." (PMID 34680213, 2021). "Moreover, NF1-deficient cancers correlated with established RAS activation signatures." (PMID 30182054, 2018). "Somatic NF1 mutations may be critical drivers in multiple cancers." (PMID 28637487, 2017).